CD38 (CD38 molecule)
Diseases named in the same sentence as CD38 in open-access papers (continued):
Sharing a sentence is not in itself a finding about the gene and the disease.
leukemia (218 papers, 2001 to 2026). A malignant (clonal) hematologic disorder, involving hematopoietic stem cells and characterized by the presence of primitive or atypical myeloid or lymphoid cells in the bone marrow and the blood. "We demonstrated that patients with lower-risk MDS and low CD34 + CD38+HSPCs entropy had an adverse outcome and that this parameter is as an independent predictive biomarker for progression free survival, leukemia free survival and overall survival." (PMID 38575672, 2024). "In HL-60 myeloblastic-leukemia cells, RA causes differentiation evidenced by a progression of cell-surface and functional markers, CD38, CD11b, and finally reactive oxygen species(ROS) production and G1/0 cell cycle arrest in mature cells." (PMID 36329484, 2022). "In clinics, CD38 was adopted as a cell activation marker and in the diagnostic/staging of leukemias." (PMID 31783629, 2019). "The majority of AML samples express cell surface CD34, and most studies of LSCs have focused on the CD34+CD38− cell compartment, which has been associated with leukemia initiation and relapse." (PMID 29466292, 2018). "In CD34-positive AML cases, CD34+CD38– cells that express aberrant leukemia-associated immunophenotypic markers are neoplastic." (PMID 24244383, 2013). "Discrimination and purification of CD34+CD38– LSC and CD34+CD38– HSC have been performed by using leukemia-associated proteins identified by us and others." (PMID 24244383, 2013). "Compared to CD38+ primitive cells, CD38 dim/− primitive cells have greater differentiation potential, lower reactivity to growth factor stimulation, and have long been considered as leukemia stem cells (LSCs) associated with leukemia." (PMID 40574795, 2025). "A retrospective analysis of more than 100 patients under 65 years of age with de novo AML indicated that higher percentages of CD34+/CD38−/CD123+ leukemia cells at diagnosis associate with enhanced probability of resistance to intensive chemotherapy and shorter disease-free survival." (PMID 33322769, 2020). "Notably, TL-induced decrease in CD38 was associated with more apoptosis in U937 than in the other leukemia cell lines." (PMID 30733502, 2019). "Among the biological CLL prognostic markers the IgVH mutation status or its surrogate markers (ZAP-70 and CD38 expression) as well as genomic aberrations may identify the subjects with more aggressive leukemia and poor prognosis." (PMID 27147570, 2016). "This hypothesis is further supported by a recent leukemia model-based study that AML cells with low ROS were enriched within the leukemia-initiating cells that had higher percentages of CD34+CD38- cells, reflecting the reverse association between ROS level and differentiation." (PMID 38434766, 2024). "In this work, we employed a Markov chain mathematical model to quantify the rates of cell state transitions between CD34+/CD38−, CD34+/CD38+, CD34−/CD38+, and CD34−/CD38− leukemia subpopulations in patients with B-ALL." (PMID 41295979, 2026). "Our analysis suggests the existence of dedifferentiating transitions to a CD34+/CD38− stem cell–like immunophenotype in leukemia samples collected from patients with B-ALL, and the tendency for these transitions is especially strong in B-ALL with BCR::ABL1." (PMID 41295979, 2026). "The therapeutic effect of CD38 CAR-T cells on leukemia progression was evaluated on days 5 and 7 post-transplantation." (PMID 39856752, 2025). "Yet leukemia-initiating capacity is detected also in CD34+CD38+ and in CD34- cell clones; which, however, in general, have a decreased capacity for leukemia initiation." (PMID 40643557, 2025). "Anti-human CD38-hAtt (hCD38-hAtt) has been shown to reduce the proliferation of leukemia and lymphoma cell lines in vitro, and to inhibit the growth of CD38-expressing xenograft tumors in immunodeficient mice." (PMID 40315226, 2025).
leukemia (continued). "Daratumumab is a human IgG1 monoclonal antibody from Janssen that binds to CD38 (first-in-class) and is utilized for treating MM, lymphoma, leukemia, and systemic AL amyloidosis." (PMID 38983860, 2024). "Leukemic stem cells are a subpopulation of leukemia cells characterized by the CD34 + CD38- phenotype, and are considered to be resistant to standard treatment." (PMID 38666914, 2024). "Two of these clusters were “leukemia-related” containing a great proportion of CD34+/CD38− hematopoietic stem cells (HSCs) or CD34+ cells with a strong co-expression of CD45RA/CD123, respectively." (PMID 38610998, 2024). "According to the cell surface marker profile, LSCs are CD34+/CD38−/CD123+ malignant cells that initiate leukemia in NOD/SCID mice with unfractionated AML." (PMID 37692500, 2024). "These xenografts have proved a better engraftment of human AML and yielded more heterogeneity in leukemia stem cell populations including CD34+ CD38+ cell populations, suggesting the critical importance of the microenvironment in vivo." (PMID 39272967, 2024). "Among the AML stem cell population, CD34+/CD38- arethe only ones capable of inducing leukemia in vivo." (PMID 38818079, 2024). "Expression of CD38 and CD49d is thought to be a poor prognostic factor as they help leukemia cells migrate and homing to secondary lymphoid organs and stimulate B-CLL cell proliferation in tandem with BCR signaling." (PMID 38560574, 2024). "The combination of apigenin with LY294002 for treatment of CD34+CD38−/low leukaemia cells, including leukaemia stem cells, induced apoptosis in these cells associated to caspase activation, mitochondrial dysfunction, and downregulation of Bcl-xL and NF-κB." (PMID 38612718, 2024). "Our initial characterization of HOSU-53 involved the immunophenotyping of treated primary AML samples, including CD38 as a marker to gate leukemia stem cells." (PMID 38646934, 2024). "Leukemic stem cells are a subpopulation of leukemia cells characterized by the CD34+CD38- phenotype considered to be resistant to standard treatment." (PMID 37754227, 2023). "As a result of the abrogation of this effect, they found that the CD34+CD38+ fraction of seven AML samples initiated leukemia in immunodeficient animals." (PMID 37735675, 2023). "CSCs were first identified in leukemia, and researchers found that only implantation of CD34 + CD38-acute leukemia (AML) cells into immunodeficient mice triggered leukemia 7)." (PMID 37213675, 2023). "In AML, the first study of CSCs was published in the late twentieth century, in which Bonnet and Dick isolated a subset of CD34+/CD38− leukemia cells." (PMID 36879313, 2023). "Various surface markers, such as CD93, CD69, and CD36, have been found to demarcate distinct subpopulations of immunophenotypically sorted HSC-like cells (CD34+CD38−) that differ in leukemia initiating activity and cell cycle status." (PMID 37653425, 2023). "As leukemia-initiating AML cells can reside in the CD34+CD38+ compartment, treatment with the recombinant antibody daratumumab against CD38 inhibits mitochondrial transfer to AML blasts, inhibiting the leukemia growth." (PMID 38169927, 2023). "In relapsed acute myeloid leukaemia (AML), a phase I trial using Plerixafor demonstrated efficacy in overcoming stromal-leukaemia protection against targeted therapy, by mobilising CD34+CD38− leukaemia cells to the periphery." (PMID 36780103, 2023). "Though CD38 is expressed on various types of leukemia including CLL and MM, the specific role of CD38 in mitochondrial transport through EVs by leukemia cells in bone marrow microenvironment is unclear." (PMID 37798791, 2023). "The combination of varying features of antigen expression is more informative in predicting survival, where CD34(+)/CD38(−)/CD123(+) representing the leukemia stem cell phenotype has prognostic relevance." (PMID 36808479, 2023).
leukemia (continued). "The rare subset that marked the CD34+CD38- population was the same as that of normal hematopoietic stem cells (HSCs), and was defined as leukemia stem cells (LSCs)." (PMID 35865470, 2022). "The course of CLL depends on the clinical stage and some molecular factors, such as CD38 or ZAP70 expression on leukemia cells or deletion 17p leukemia." (PMID 35158937, 2022). "Due to the high expression of CD38 in leukemia cells, DARA was added (16 mg/kg dose weekly for three weeks), and CR was achieved." (PMID 36313735, 2022). "Impact of leukemia stem cell frequency (CD34/CD38/CD123) at diagnosis on overall survival in 80 acute myeloid patients." (PMID 35530356, 2022). "Marinov J was the first to evaluate CD38 expression in 72 leukemia patients and noted that the positive rate of CD38 was up to 75% in myeloid tumors and acute non-T lymphoblastic leukemia." (PMID 36313735, 2022). "Unfortunately, most patients treated with TKs, such as dasatinib and imatinib, experience leukemia cell persistence in CML because the leukemia stem cells (CD34 + CD38-) enter the G0 phase, in which the cells become quiescent, and can thus survive." (PMID 36080390, 2022). "Leukemia is now considered to be a stem cell disease with its characteristic refractory nature being blamed on a rare population of CD34+/CD38- LSCs." (PMID 35530356, 2022). "Since conventional flow cytometry evaluation showed significant differences between leukemia cells derived from High and Standard-risk patients when two surface markers were analyzed (sGRP78 in combination with CD34, CD38, CD10 or CXCR4)." (PMID 35149705, 2022). "CD38-targeting antibodies, like daratumumab, have been approved for the treatment of MM and tested against lymphoma and leukemia in multiple clinical trials." (PMID 35765110, 2022). "For instance, BM MSCs co-cultured with leukaemia cell lines had different degree of stemness (CD34+CD38− or CD34+CD38+ or CD34− cells) upregulated differentially with the expression of sets of genes." (PMID 35629139, 2022). "CD34+CD38– is the most widely used CSC marker in leukemia, whereas CD133+ was described as the first brain CSC marker." (PMID 33763422, 2021). "To test if CD38 inhibition affects leukemia growth in AML, we applied the monoclonal antibody daratumumab on a series of different AML cell lines in mono-culture, as well as in co-culture to elaborate putative niche-mediated effects of daratumumab." (PMID 34764342, 2021). "CD123 expression on NPM1mut cells was already reported by our group while characterizing NPM1mut CD34+CD38− leukemia-initiating cells in xenograft experiments." (PMID 33525388, 2021). "Initial studies suggested that CSCs in leukemias (LSCs) are restricted to the CD34+CD38- phenotype, shared with normal HSCs (hematopoietic stem cells), though this statement has been redefined." (PMID 33801964, 2021). "In summary, CD38 inhibition interferes in AML cell trafficking resulting in lower leukemia burden particularly in the peripheral blood, but overall does not show robust anti-leukemic activity as monotherapy or in combination with cytarabine in vivo." (PMID 34764342, 2021). "In general, CD34+CD38− AML cell populations display a higher leukemia-initiating cell frequency than CD34+CD38+ AML cell populations." (PMID 34012921, 2021). "Primitive CD34+/CD38− HSPCs were suggested to be leukemia-initiating cells for RUNX1-RUNX1T1, PML-RARα, and KMT2A-MLLT3 AML." (PMID 33803739, 2021). "Given the obvious redistrubition of leukemia cells after daratumumab treatment, we wondered if CD38 inhibition affects AML cell trafficking in vivo." (PMID 34764342, 2021). "For example, purified CD34+CD38− leukemia stem cells regenerated cells with the same markers as well as distinct subpopulations carrying CD34+CD38+ markers." (PMID 32953979, 2020). "In our model, further experiments using different subgroups expressing CD34 or CD38 are needed to determine the metabolic dependency of methionine in MLLr leukemia-initiating cells." (PMID 32456310, 2020).
leukemia (continued). "These include immunophenotypic markers of leukemia cells (CD38 and ZAP-70) assessed by flow cytometry in the immunoglobulin variable region of the heavy chain gene (IgVH)." (PMID 33147729, 2020). "For this aim, we have functionalized our HC-NPs with an antibody against CD38 specific for leukemia cells." (PMID 31510037, 2019). "TL and SKF inhibited chemotactic peptide fMLP-induced response linked to TRPV2 Ca2+ activity, and down-regulated expression of surface marker CD38 involved in leukemia and lung airway inflammation." (PMID 30733502, 2019). "3G3 seemed to be a good candidate with the potential to offer better therapeutic efficacy, especially in CD38+ leukemia patients." (PMID 31118070, 2019). "Recently, our team screened a mouse-anti-CD38 mAb, 3G3, by hybridoma technology, which showed good anti-leukemia activity in vitro." (PMID 31118070, 2019). "It is now generally accepted that CD38+ leukemia patients have a shorter progression-free interval, require earlier and more frequent treatments, and ultimately lower survival rate." (PMID 31118070, 2019). "Further, CD34+CD38− cells in KG-1, KG-1a, TF-1, and primary leukemia cells were more sensitive to HHT and ATO." (PMID 31307525, 2019). "Our results demonstrate that Nanog is overexpressed in patient-derived CD34+ leukemia cells and in CD34+CD38- LSCs from leukemia cell lines." (PMID 30013477, 2018). "In 1994 it was shown that leukemic cells possessing the CD34+CD38- cell-surface markers were able to initiate leukemia in severe combined immunodeficiency (SCID) mice, while CD34+ or certain CD34+CD38+ expressing cells were unable to do so." (PMID 30320108, 2018). "Our results showed that the CD25-negative population of Lin–CD34+CD38– or Lin–CD34+ cells from CD25-positive AML patients reconstituted leukemia at the primary or secondary transplantation in the absence of the CD25-positive population." (PMID 30550585, 2018). "Nanog is overexpressed in cancer cells and in this study, we found that Nanog is overexpressed in CD34+ cells of patients with AML and in CD34+CD38- cells of leukemia cell lines." (PMID 30013477, 2018). "Accumulating evidence shows that CD34+CD38- leukemia stem cells (LSCs) are responsible for drug resistance, metastasis, and relapse of leukemia." (PMID 30013477, 2018). "Here, we report the in vitro and in vivo activity of DS in combination with copper (Cu) against CD34+/CD38+ leukemia stem-like cells sorted from KG1α and Kasumi-1 AML cell lines, as well as primary CD34+ AML samples." (PMID 28518151, 2017). "Using the difference in ALDH activity in combination with detection of aberrant leukemia-associated marker expression, CD34+CD38− HSCs and CD34+CD38− LSCs from AML bone marrows have been purified." (PMID 28665351, 2017). "Last, to assess in vivo antitumor effects of DS/Cu, CD34+/CD38− KG1α cells were grafted in mice to a leukemia mouse model as described in detail in Methods." (PMID 28518151, 2017). "Both articles evaluated the expression of CD82 in the self-renewing leukemia stem cell (LSC) compartments (CD34+/CD38− cells) and the CD34+/CD38+ compartments of AML cells." (PMID 28646224, 2017). "Here we show that cordycepin reduces CD34+CD38− cells in U937 and K562 cells and induces Dkk1 expression via autocrine and paracrine regulation in leukemia and mesenchymal stromal/stem cells (MSCs)." (PMID 28266575, 2017). "The idea to identify CSCs by flow cytometry comes from leukaemia where LSCs constitute a population of CD34+CD38- cells capable of generating leukaemia in immunosupressed mice." (PMID 27766946, 2016). "Normal CD34+CD38– cells showed relatively less apoptotic response to alantolactone treatment comparing with the response to leukemia stem cells at 10 μM." (PMID 27658462, 2016). "In contrast, the traditional chemotherapy drug Ara-C exhibited little apoptosis when tested against total primary leukemia cells abf CD34+CD38- cells at concentrations of 5 and 10 μM." (PMID 27658462, 2016).
leukemia (continued). "K562 represents CML blast crisis, consisting of primitive blast-like leukemic cells, while the CD34+CD38− population of KG1a demonstrated the leukemia stem-like cell property in vivo." (PMID 27110755, 2016). "These pre-LSC are fundamentally distinct from the tumor initiating, CD34+ CD38− leukemia stem cells (LSC or leukemia-initiating cells, LIC) described extensively over the past two decades." (PMID 27597933, 2016). "Meanwhile, KG1a cells exhibit an LSC-like phenotype with high levels of CD34 expression (98.6%) and low levels of CD38 expression (24.6%), so it was considered as a leukemia stem-like cell line." (PMID 27542251, 2016). "It has been reported that LSCs which bear the CD34+CD38– immunophenotype play the major role for initiation of leukemia, drug resistance, and recurrence of leukemia, and are related to minimal residual disease (MRD)." (PMID 27658462, 2016). "AML is typically a stem cell-driven disease, and the existence of leukemia stem cells (LSCs) was first identified (CD34 + CD38-) by JE Dick in 1994; these cells extremely promote AML progression, chemo-resistance and recurrence." (PMID 25890196, 2015). "Whole genome microarray analysis of leukaemia initiating cells comprising the Lin−CD34+CD38− and Lin−CD34+CD38+ from AML patients showed reduced levels of NOTCH target gene expression in comparison with the CD34+ bone marrow cells from normal donors." (PMID 25711903, 2015). "We identified Ph+ leukemia cells using the human CD38 antibody and analyzed apoptosis with Annexin-V combined with propidium iodide by flow cytometry." (PMID 24860788, 2014). "Discrimination between putative leukemia stem cells and normal hematopoietic stem cells in this large-scale study allowed to demonstrate the clinical importance of putative CD34+CD38- leukemia stem cells in AML." (PMID 25244440, 2014). "CD34 and CD38 were used as markers in the original studies of leukemia stem cells which were first identified at the beginning of research." (PMID 24689055, 2014). "The goal of the current study is to investigate the effect of nilotinib on drug retention in leukemia-initiating CD34+CD38− stem cells and characterize the interactions of nilotinib with ABC transporters in primary leukemic blasts." (PMID 24651611, 2014). "In leukemia, for instance, stem cells are enriched in the CD34+ fraction and further enriched in the CD34+/CD38− fraction, yet the ‘real’ leukemia-initiating cell is believed to be represented by an even smaller subpopulation of CD34+/CD38− cells." (PMID 25216521, 2014). "The percentage of leukemia initiating cells (FISH+CD34+CD38-) was then quantified as the value of the percentage of FISH-positive cells multiplies the percentage of CD34+CD38-cells in the blast (CD45dimSSClow)." (PMID 24517186, 2013). "In acute myeloid leukemia (AML), the leukemia initiating cells (LICs) or leukemia stem cells (LSCs) is found within the CD34+CD38- cell compartment." (PMID 24517186, 2013). "This putative normal HSC, CD34+CD38– ALDHbright, cell population of 7 of these 19 CD34-positive AML cases was essentially devoid of cells with the leukemia-specific cytogenetic abnormalities FLT3-ITD and/or mutated NPM1." (PMID 24244383, 2013). "CD34+CD38- leukaemia cells are largely quiescent and reported to be resistant to chemotherapeutic drugs." (PMID 23013471, 2012). "Initially, it was thought that the LSC resided in the CD34+CD38- compartment, but many anti-CD38 antibodies, including those utilized in the original isolation of LSCs inhibit engraftment of CD34+CD38+ leukemia cells through an Fc-dependent mechanism." (PMID 22876360, 2012). "The combination of HB2-SAP (anti-CD7) plus OKT10-SAP (anti-CD38) administered in 3 × 10 μg i.v. doses significantly increased survival time and the number of leukemia-free animals (60%)." (PMID 22069735, 2011).